ENSG00000221093
Synonyms: LOC124900263
Gene: Small nucleolar RNA gene on chromosome 8 (56,121,242 to 56,121,352, reverse strand). Ensembl gene ENSG00000221093.
Gene Ontology:
Biological process: RNA processing
Cellular component: nucleolus
Homologues: Orthologues: mouse Gm22673 (74% identical), rat Snora3c (74% identical), mouse Gm56083 (61% identical), rat LOC120102628 (59% identical), rat LOC120102629 (59% identical), mouse Gm25539 (58% identical). Paralogues in human: SNORA3B (78% identical), SNORA3C (76% identical), SNORA3A (67% identical).